Y_RNA (Y RNA )
Gene: Miscellaneous RNA gene on chromosome 4 (185,415,973 to 185,416,086, reverse strand). Ensembl gene ENSG00000207231.
Homologues: Orthologues: chimpanzee Y_RNA (100% identical), macaque Y_RNA (94% identical). Paralogues in human: Y_RNA (84% identical), RNY1P5 (82% identical), Y_RNA (82% identical), RNY1P2 (81% identical), Y_RNA (81% identical), Y_RNA (80% identical), RNY1 (79% identical), RNY1P6 (79% identical), Y_RNA (79% identical), Y_RNA (78% identical), Y_RNA (77% identical), RNY1P1 (76% identical), and 92 more.